IGF1 (insulin like growth factor 1)
Diseases named in the same sentence as IGF1 in open-access papers (continued):
Sharing a sentence is not in itself a finding about the gene and the disease.
Hyperinsulinemia (continued). "Thus, hyperinsulinemia can increase circulating IGF1 levels, which can promote tumor growth and metastasis." (PMID 36295107, 2022). "Poor glycemic control can lead to hyperinsulinemia, and insulin may exert mitogenic effects through the insulin-like growth factor 1 (IGF-1) receptor, thereby stimulating cell proliferation and inhibiting apoptosis." (PMID 36387876, 2022). "In addition, chronic hyperinsulinemia lowers the hepatic expression of IGFBPs (BP-1 and BP-2), resulting in increased plasma levels and bioavailability of free IGF-1." (PMID 34208601, 2021). "In hyperinsulinemia, an up-regulation of GH receptor and hepatic IGF-1 synthesis can be observed." (PMID 34208601, 2021). "Hyperinsulinemia may contribute to colorectal cancerogenesis directly by stimulating colonic cell proliferation and indirectly by increasing the level of insulin-like growth factor 1 (IGF-1)." (PMID 33922197, 2021). "Hyperglycemia may also directly promote hyperinsulinemia and indirectly induce tumor development by increasing IGF-1 function." (PMID 34975754, 2021). "As cited above, hyperinsulinemia can increase IGF-1 production." (PMID 34574647, 2021). "Hyperinsulinemia causes hyperandrogenism through elevation of sex hormone free fractions due to decreased SHBG (sexual hormone binding globulin), increased hepatic insulin-like growth factor-1 (IGF-1) production, and/or increased IGF-1 bioavailability through a reduction in IGFBP-1 generation." (PMID 34574647, 2021). "Wrist circumference has also been suggested to be an easy and well-known index of skeletal frame size, and also a good surrogate to assess bone metabolism in relation to hyperinsulinemia, since insulin-like growth factor 1 (IGF 1) levels are major determinants of bone geometry." (PMID 34903195, 2021). "According to the authors, hyperinsulinemia-mediated islet and β-cell insulin/IGF-1 resistance may be involved in the decomposition of β-cells." (PMID 34208601, 2021). "Moreover, hyperinsulinemia (resulting from subcutaneous insulin injection) stimulates hepatic expression of IGF-1 and elevates its bioavailability via depletion of IGFBP-1/2." (PMID 34535145, 2021). "Hyperinsulinemia-mediated islet and β-cell insulin/IGF-1 resistance, often overlooked, could be a key factor that contributes to β-cell decompensation." (PMID 32150819, 2020). "Hyperinsulinemia induces the production of insulin-like growth factor-1 (IGF-1) by the liver." (PMID 32907593, 2020). "Furthermore, IGF-1 and hyperinsulinemia increase the bioavailability of sex hormones by inhibiting sex-binding globulin synthesis in liver and lead to growth and progression of hormone-dependent cancers." (PMID 32325965, 2020). "Among the biological factors are hyperglycemia, hyperinsulinemia, overproduction of insulin-like growth factor-1 (IGF-1), increased expression of the IGF-1 receptor, and increased secretion of inflammatory cytokines, such as interleukin 6 (IL-6) and tumor necrosis factor alpha (TNF-α)." (PMID 32473631, 2020). "Its putative neuroprotective properties, when taken with meals, could reduce hyperinsulinemia by downregulating insulin-like growth factor-binding protein and increasing free insulin-like growth factor-1 (IGF-1)." (PMID 32244373, 2020). "Patients with either hyperglycemia or hyperinsulinemia might decrease the production of hepatic proteins and binding capacity subsequently increased the concentration of free IGF-1 value in the body." (PMID 30705329, 2019). "Hence, hyperinsulinemia and elevated bioavailable IGF-1 levels support a carcinogenic and early tumor growth setting in some cancers, such as in the case of CRC, where this association has been determined, independent of adiposity." (PMID 31596902, 2019).
Hyperinsulinemia (continued). "Our results showed that in chronic diosgenin and fenugreek treatment the basal level of thyroid hormones, especially T3 significantly decreased, but the consequent IGF-1 elevation in response to hyperinsulinemia in the steady state effectively balances this reduction in the diosgenin groups." (PMID 31080828, 2019). "Additionally, hyperinsulinemia in PCOS is known to increase the bioavailability of IGF1 via the downregulation of its carrier protein, i.e., IGFBP1." (PMID 30975191, 2019). "IGF-1 elevation might have appeared as a result of hyperinsulinemia and the significantly increased GH levels." (PMID 31080828, 2019). "In addition, hyperinsulinism, a prevalent metabolic disorder in obese women, increases bioavailability of androgen, IGF-1 and lipogenesis of sebaceous cells." (PMID 31477085, 2019). "Evidence suggests that hyperinsulinemia may play a key role directly or by enhancing the bioavailability of insulin-like growth factor-1 (IGF-1), a stimulant for tumor growth and development." (PMID 30740588, 2018). "In addition, hyperinsulinemia upregulates the expression and activity of insulin-like growth factor-1 (IGF-1)." (PMID 30154386, 2018). "Yet, hyperinsulinemia by increasing the bioavailability of IGF-1 and IGF-2 may favor tumor progression and the activation of IGF-1R, IR/IGF-1R hybrids, IR-A, and their interaction with other molecular partners." (PMID 30513575, 2018). "Hyperinsulinemia might contribute to the proliferation of cancer cells by activating the signaling pathway of IGF-1, which could lead to the occurrence of cancer." (PMID 30254671, 2018). "Hyperglycemia and hyperinsulinemia also increase IGF-1 levels, which may promote tumor growth by enhancing cell proliferation and inhibiting apoptosis." (PMID 29312558, 2017). "Experimental and epidemiological evidence indicate that hyperinsulinemia and elevated levels of insulin-like growth factor- 1 (IGF-1) may promote colorectal tumorigenesis by stimulating mitogenesis and inhibiting apoptosis." (PMID 29259258, 2017). "T2DM combined with its relative hyperinsulinemia and hyper-insulin-like growth factor 1 (IGF-1) production may also accelerate the development of HCC." (PMID 28515345, 2017). "Hyperinsulinism may contribute to hepatic IGF-1 formation leading to increased IGF-1 concentrations." (PMID 29163361, 2017). "We therefore examined metabolic pathways known to be affected by hyperinsulinemia/IGF-1." (PMID 30873458, 2016). "Additionally, hyperinsulinemia also leads to increase the level of bioactive IGF-1, which is a potent mitogen that can result in carcinogenesis." (PMID 26901856, 2016). "Additionally, changes in the metabolic microenvironments of obese men resulted in compensatory hyperinsulinemia as well as increased levels of insulin-like growth factor 1, both of which were proved to encourage carcinogenesis and inhibit apoptosis." (PMID 26542246, 2015). "The hyperinsulinemia may enhance synthesis of insulin-like growth factor 1 (IGF-1) and its bioavailability by decreasing the IGF binding proteins (IGFBP)." (PMID 26347815, 2015). "Disruption of the circadian organization of this host/cancer balance by LAN-induced melatonin suppression leads to a 24-hour a day constitutive hyperinsulinemia/hyperglycemia accompanied by elevated blood IGF-1 levels in the host and runaway constitutive metabolism and growth in the tumor." (PMID 25099274, 2014). "The underlying mechanisms of tumorigenesis in T2DM seem to be related to insulin resistance, hyperinsulinemia, elevated levels of IGF-1, and hyperglycemia with the latter driving ATP production in cancer cells through the glycolytic pathway, a mechanism known as the Warburg effect." (PMID 23415113, 2013). "Hyperinsulinism is also responsible for stimulating insulin-like growth factor-1 (IGF-1) secretion by the liver, which may act as a growth factor of multiple malign tumors in vivo, such as prostate carcinoma." (PMID 24282613, 2013).
Hyperinsulinemia (continued). "Prolonged hyperinsulinemia increases endogenous levels of insulin-like growth factor-1 (IGF-1)." (PMID 23319943, 2012). "Through the interaction with insulin-like growth factor axis protein 1(IFG-1) and insulin-like growth factor binding proteins, hyperinsulinemia also might increase the level of IGF-1." (PMID 22839452, 2012). "From this perspective it can be hypothesized that hyperinsulinemia could have a mitogenic effect on osteoblasts and their differentiation by stimulating the IGF-1 signaling pathway." (PMID 22451239, 2012). "Furthermore, hyperinsulinemia was shown to indirectly increase bioavailability of IGF-1 by regulating the expression levels of IGF-binding proteins." (PMID 22174655, 2011). "Similarly, compensatory hyperinsulinemia is associated with reductions in insulin-like growth factor binding protein-1 (IGFBP-1), corresponding to higher cellular concentrations of free insulin-like growth factor-1 (IGF-1)." (PMID 22253996, 2010). "Furthermore, hyperinsulinemia promotes cancer progression by activating the insulin/IGF-1 axis." (PMID 41310487, 2025). "Therefore, hyperinsulinemia and the increase in bioavailable IGF-1 may be involved in tumor initiation and progression in insulin-resistant patients." (PMID 38392069, 2024). "In horses and ponies, hyperinsulinemia alters the behavior of lamellar cells, resulting in hyperinsulinemia-associated laminitis (HAL) which has been linked to proliferation and epidermal lamellar cell dysfunction due to insulin-like growth factor 1 (IGF-1) receptor activation." (PMID 38396558, 2024). "Furthermore, insulin may control IGF-1 production by altering the levels of IGF-1 binding proteins and/or by hyperinsulinemia-induced promotion of hepatic growth hormone receptor expression and IGF-1 synthesis." (PMID 37106164, 2023). "Chronic hyperinsulinemia can develop from long-term CHO consumption, and it has been claimed that hyperinsulinemia may raise the risk of OC by activating numerous pathways that include insulin-like growth factor 1 (IGF-1)." (PMID 37686842, 2023). "The IGF-1 system may also be involved in the effects of hyperinsulinemia on carcinogenic pathways." (PMID 37106164, 2023). "Besides, hyperinsulinemia observed in T2DM can change the levels of insulin-like growth factor binding protein (IGFBP), insulin-like growth factor 1 (IGF-1), and SHBG, which in turn cause an increase in androgen secretion from the ovaries and adrenals, and ultimately anovulation." (PMID 37424869, 2023). "In addition, hyperinsulinemia also exerts its proliferative effects indirectly by reducing the liver production of IGF-1-binding proteins to increase the biologically active free IGF-1." (PMID 35933633, 2022). "Thus, in a state of hyperinsulinemia, IGF-1 levels may significantly rise and induce mitogenic effects in the body." (PMID 35457158, 2022). "In addition, hyperinsulinemia mediates the production of IGF-1, inhibits the production of IGFBP in the liver, increases the bioavailability of IGF-1 and stimulates further tumor growth through excessive activation of the PI3K-Akt-mTOR pathway and Ras-MAPK pathway." (PMID 33842335, 2021). "Chronic hyperinsulinemia might lead to neoplasm development directly acting as a mitogenic factor itself, but also through its deep interplay with sex hormones and other growth factors pathways, e.g., insulin growth factor 1 (IGF-1)." (PMID 34205356, 2021). "Hyperinsulinemia could indirectly promote carcinogenesis via IGF-1." (PMID 34535145, 2021). "Prolonged hyperinsulinemia may lead to increased IGF-1 secretion." (PMID 32351453, 2020). "Therefore, it is possible that elevated levels of IGF-1 induced by hyperinsulinemia could also promote HCC growth." (PMID 26441826, 2015).
Hyperinsulinemia (continued). "IGF-1 is a peptide growth factor that shares ∼50% sequence homology with insulin and is produced primarily by the liver following stimulation by growth hormone, although hyperinsulinemia and hyperglycemia can lead to increased hepatic IGF-1 production independent of growth hormone signaling." (PMID 23967401, 2013). "A central feature is hyperinsulinemia: T2DM patients often exhibit elevated insulin and IGF-1 levels, particularly in the early stages of the disease, which serves as a growth signal for epithelial cells." (PMID 41374093, 2025). "Hyperinsulinemia reduces the levels of IGF-binding proteins (IGFB1 and IGFB2), leading to higher free IGF-1 bioavailability, which in turn promotes mitogenesis and inhibits apoptosis in endometrial cells." (PMID 41050662, 2025). "VAT induces hyperinsulinemia by the secretion of IGFBP1 and 2, increases free insulin and IGF-1, stimulates cell proliferation, inhibits apoptosis, and favors angiogenesis." (PMID 38785834, 2024). "It is clear that IR and hyperinsulinemia directly affect the synthesis of the IGF-1 binding protein, which eventually results in increased circulating concentration of IGF-1." (PMID 39189167, 2024). "Both IR and hyperinsulinemia increase the serum level of insulin-like growth factor 1 (IGF-1) and the biological activity of IGF-1." (PMID 37361533, 2023). "Hyperinsulinemia in portal vein leads to enhanced responsiveness of liver GH receptors and IGF-1 production, pointing towards a mutually amplifying loop between GH-IGF-1 axis and insulin." (PMID 36882643, 2023). "Regarding stimulation of the IGF1 signaling pathway, hyperinsulinemia seen in T2DM reduces IGF-binding protein levels and enhances bioavailable IGF levels afterward." (PMID 38004062, 2023). "The mammalian target of the rapamycin (mTOR) pathway is coupled to the insulin/IGF-1 signaling pathway; thus, NAFLD has a high probability of occurring due to hyperinsulinemia." (PMID 36831551, 2023). "Hyperinsulinemia downregulates IGF binding proteins (IGFBP) concentrations and increases free IGF-1 which promotes cellular proliferation and inhibits apoptosis." (PMID 37221355, 2023). "In our cohort, we highlighted a statistically significant correlation between patients with hyperinsulinemia and other metabolic/anthropometric parameters such as weight, BMI, waist circumference, hip circumference, WHtR, HDL, triglycerides, IGF-1, and fT3." (PMID 37754306, 2023). "Second, hyperinsulinemia reduces insulin-like growth factor (IGF) binding protein 1 and 2, which usually binds and inactivates IGF-1, thereby increasing free IGF-1 which is increased in VO." (PMID 33777773, 2021). "In metabolic syndrome, the amount of bioavailable IGF1 increases via hyperglycemia-induced suppression of IGFBP synthesis and/or hyperinsulinemia-induced promotion of hepatic GH receptor expression and IGF1 synthesis." (PMID 33224954, 2020). "The decline in synthesis of insulin-like growth factor-1 (IGF-1) binding protein and activation of IGF-1 by hyperinsulinemia can also lead to tumor cell proliferation." (PMID 33335232, 2020). "Hyperinsulinemia directly affects ovarian theca cells through the mediation of IGF-1, or by diminished production of IGF-1BP in the liver and increases IGF-1 and IGF-2 levels." (PMID 30944702, 2019). "Insulin resistance results in hyperinsulinemia, which reduces the levels of IGF-1 binding proteins (IGFBP1, IGFBP2) and thereby increases IGF-1 availability." (PMID 30380719, 2018). "Preclinical studies found that metformin reduces insulin and IGF-1 level in serum and stables blood glucose level through AMPK pathway and thus reverses the tumor promoting effect driven by hyperinsulinemia and hyperglycemia." (PMID 28271076, 2017). "Hyperinsulinism decreases hepatic secretion of IGF binding protein (IGFBP), further increasing evels of free IGF-1." (PMID 28261315, 2017). "Hence, hyperinsulinemia and high level of IGF-1 may be its main mechanisms." (PMID 26901856, 2016).
Hyperinsulinemia (continued). "Due to this last evidence, in a condition of hyperinsulinemia, IGF1R can be activated both directly by the high circulating levels of insulin and, indirectly, through insulin-mediated upregulation of IGF-1." (PMID 26171112, 2015). "Chronic hyperinsulinemia inhibits the production of IGF-binding protein 1 (IGFBP-1) and IGFBP-2, which results in the increased bioavailability of IGF-1." (PMID 25402501, 2014). "As hyperinsulinemia can also affect the expression level of IGFI and IGFII, we used semi-quantitative PCR to compare the levels of both Igf1 and Igf2 mRNA in MKR+/+ and control mice." (PMID 22226054, 2012). "We validated the expression of Hnf4α, a gene downregulated during hyperinsulinemia that also participates in the PPAR pathway, underscoring the importance of IGF-1 to the metabolic effects of CR." (PMID 23342276, 2012). "Chronic hyperinsulinemia decreases IGF-binding protein 1 and IGF-binding protein 2 concentrations in blood and other local tissues, which results in an increase in bioavailable free IGF-1." (PMID 41376649, 2026). "In fact, hyperinsulinemia not only directly engages insulin and IGF-1R but also amplifies mitogenic signalling by boosting free IGF-1 availability, which activates IGF-1R, initiating signalling cascades such as PI3K, inhibiting apoptosis, and promoting protein synthesis." (PMID 40806650, 2025). "Overall, we describe the regulation of IGF1 signal modulators and highlight the anorexigenic role of IGF1 in the ARC hypothalamus, and we provided evidence that hyperinsulinemia induces cellular IGF1 resistance through reduced IGF1R levels in a PI3K-FOXO1–dependent manner." (PMID 40105689, 2025). "In fact, chronic hyperinsulinemia decreases the concentration of IGF-binding protein 1 (IGFB1) and IGF-binding protein 2 (IGFB2), which increase the bioavailability of free IGF-1, with a concomitant change in the cellular environment (mitogenesis and antiapoptosis." (PMID 38396914, 2024). "Comparing patients with and without hyperinsulinemia, we found statistically significant differences in weight, BMI, WC, HC, IGF-1, uric acid, VLDL, triglycerides, and basal insulin levels." (PMID 38920551, 2024). "Hyperinsulinemia may also decrease the levels of IGF-1 binding protein, thereby increasing the bioavailability of IGF-1, which further supports cell proliferation." (PMID 38535034, 2024). "Hyperinsulinemia or hyperprolactinemia can alter the distribution of circulating IGF-1, which can promote growth even in the absence of growth hormone." (PMID 38828392, 2024). "There is a suggestion that hyperglycemia and hyperinsulinemia, typical features of T2DM, may reduce the hepatic production of IGFBP3, increasing the levels of free IGF-1." (PMID 38392069, 2024). "First, hyperinsulinemia observed in patients with T2DM can impede cell apoptosis and promote cell proliferation through stimulation of insulin and the insulin-like growth factor-1 (IGF-1) pathway." (PMID 38004062, 2023). "Hyperinsulinemia, which is common in the course of PDAC, can reduce the level of IGF-1." (PMID 37373743, 2023). "Since insulin receptors are widely expressed in CRC cells, controlling hyperglycemia can reduce hyperinsulinemia and may, in turn, hamper induction of EMT, insulin/IGF-1, and PI3K-AKT-mTOR signals, leading to continuous survival and division of CRC." (PMID 37568291, 2023). "Additionally, hyperinsulinemia also leads to a decreased level of IGF-binding protein 1,2, and 3 resulting in an increased level of bioavailable IGF-1." (PMID 33920079, 2021). "On the one hand, hyperinsulinemia may enhance the bioavailability of IGF-1 and IGF-2 by inhibiting the synthesis of IGFBP-1/2 and promoting the production of IGF-1 in the liver." (PMID 33815885, 2021).